PINX1 (PIN2 (TERF1) interacting telomerase inhibitor 1 )
Diseases named in the same sentence as PINX1 in open-access papers (continued):
Sharing a sentence is not in itself a finding about the gene and the disease.
cervical squamous cell carcinoma (4 papers, 2016 to 2025). A squamous cell carcinoma arising from the cervical epithelium. "First, only a single study reported the prognostic value of PINX1 expression in each of the following: cervical squamous cell carcinoma, esophageal squamous cell carcinoma, and glioma, respectively." (PMID 30079348, 2018). "In cervical squamous cell carcinoma and endocervical adenocarcinoma (CESC), which is featured by short telomeres and high telomerase activity, PinX1-TID efficiently inhibits cancer stemness traits by primarily targeting telomerase activity." (PMID 39634130, 2025). "However, among the 14 studies included in this meta-analysis, 3 reported on cervical squamous cell carcinoma, esophageal squamous cell carcinoma, and glioma where PINX1 expression has been reported to have an opposite prognostic effect compared to the pooled outcome." (PMID 30079348, 2018). "Interestingly, knockdown of PinX1 dramatically enhanced paclitaxel cytotoxicity to cervical squamous cell carcinomas cells and knockdown of PinX1 substantially increased ESCC (oesophageal squamous cell carcinoma) cells' therapeutic efficacy of radiation both in vitro and in vivo." (PMID 27556185, 2016).
colorectal cancer (4 papers, 2017 to 2025). A primary or metastatic malignant neoplasm that affects the colon or rectum. "In this study, we revealed that PinX1 is highly expressed in colorectal cancers (CRC) and promotes tumor cell proliferation." (PMID 40639785, 2025). "Both the 5-year OS and 5-year DFS in patients with colorectal cancer are lower in patients with low/negative expression of PinX1 protein compared with that in patients with high/moderate expression of PinX1 which is consistent with our current findings." (PMID 28815183, 2017).
esophageal squamous cell carcinoma (4 papers, 2016 to 2024). Esophageal squamous cell carcinoma (ESCC) is a type of esophageal carcinoma (EC) that can affect any part of the esophagus, but is usually located in the upper or middle third. "For example, one study demonstrated that high expression of PinX1 in esophageal squamous cell carcinoma is associated with a patient’s chemoradiotherapy resistance and can predict his/her survival." (PMID 28978030, 2017). "Additionally, we found PIN2/TERF1-interacting telomerase inhibitor (PinX1), a telomerase binding factor, induces radioresistance through improved telomere stability in esophageal squamous cell carcinoma(ESCC)." (PMID 38431575, 2024). "Moreover, the relationship between PINX1 expression and response to chemoradiotherapy was considered a clinical parameter in cervical and esophageal squamous cell carcinomas, the mechanism of which has not been determined." (PMID 30079348, 2018).
glioma (4 papers, 2014 to 2022). A benign or malignant brain and spinal cord tumor that arises from glial cells (astrocytes, oligodendrocytes, ependymal cells). "In contrast, there is evidence that PINX1 expression is associated with poor survival in glioma patients because it promotes cell proliferation." (PMID 36142793, 2022). "Specific siRNA molecules, delivered by mPEG-PEI-SPION, were employed to knockdown the PIN2-interacting protein 1 (PinX1) gene in C6 glioma cells." (PMID 24940406, 2014). "In the present study, PinX1 was knocked-down in C6 cells and cell viability was analyzed to confirm the potential of PinX1 as a target gene for the treatment of gliomas." (PMID 24940406, 2014). "Furthermore, gliomas were treated with a combination of PinX1-siRNA and DOX, with the aim of increasing the efficiency of the treatment and decreasing the side effects." (PMID 24940406, 2014). "The aims of the present study were to determine whether mPEG-PEI-SPION may be a device for siRNA delivery into C6 cells and whether the specific silencing of PinX1 by siRNA may improve the cytotoxic effect of DOX in C6 glioma cells." (PMID 24940406, 2014). "Therefore, mPEG-PEI-SPION was shown to be viable for siRNA delivery into C6 cells and coadministration of DOX with PinX1-siRNA may be a potential therapeutic method for inhibiting gliomas." (PMID 24940406, 2014). "Of the eight investigated genes involved in telomere maintenance and telomerase regulation, three (PINX1, TNKS, and TNKS2) were found to be downregulated in all glioma cell lines when compared to individual controls." (PMID 36142793, 2022).
nasopharyngeal carcinoma (4 papers, 2012 to 2025). A carcinoma arising from the nasopharyngeal epithelium. "Here we show that PinX1 is essential for down-regulation telomerase activity of nasopharyngeal carcinoma." (PMID 22316341, 2012).
atherosclerosis (3 papers, 2017 to 2021). A disease characterized by the build-up of fatty material and calcium deposition in the arterial wall resulting in partial or complete occlusion of the arterial lumen. "A relevant study showed that the PINX1 mutations increased the risk of carotid intima media thickness, which is used to determine atherosclerosis, a chronic formation process caused by excessive cholesterol deposition in the arterial intima." (PMID 29371971, 2017). "TRIP6, PINX1, and ERI1 have notably been associated with blood pressure, triglyceride levels, HDL cholesterol, diabetes mellitus, and atherosclerosis." (PMID 34753499, 2021). "The gene-based association identified genes (TRIP6, PINX1 and ERI1) were significantly associated with expression change in the whole blood and lung and have previously been associated with blood pressure, triglyceride levels, HDL cholesterol, diabetes mellitus and atherosclerosis." (PMID 34753499, 2021).
hepatocellular carcinoma (3 papers, 2014 to 2017). A malignant tumor that arises from hepatocytes. "Moreover, PinX1 overexpression significantly suppresses the growth of hepatocellular carcinoma cells, whereas PinX1 inhibition potently enhances cell growth." (PMID 27556185, 2016).
liver cancer (3 papers, 2011 to 2017). An epithelial or non-epithelial malignant neoplasm that arises from the liver. "This region is also a common integration site for hepatitis B virus, a well-known major risk factor in liver cancer and PinX1 is reduced in ~ 40% hepatitis B virus-related liver cancer." (PMID 22021332, 2011).
bladder cancer (2 papers, 2012 to 2017). "All of the SNPs in TEP1 were associated with increased risk, and all SNPs except one in PINX1 were associated with reduced risk of bladder cancer." (PMID 22363464, 2012). "In addition to TEP1, we found high significance in a SNP on the PINX1 gene and lower bladder cancer risk." (PMID 22363464, 2012).
bladder urothelial carcinoma (2 papers, 2013 to 2017). "With the exception of the high frequency of PinX1 gene deletion, we also found that PinX1 genetic mutations occurred in some types of human cancers, including bladder urothelial carcinoma, lung adenocarcinoma, and melanoma." (PMID 28978030, 2017). "However, another study showed that PinX1 expression in bladder urothelial carcinoma was significantly down-regulated at both the mRNA and protein levels when compared with normal tissue." (PMID 28978030, 2017). "However, the possible involvement of PinX1 and its clinical/prognostic significance in urothelial carcinoma of the bladder (UCB) are unclear." (PMID 24268029, 2013). "Our results demonstrated that PinX1 gene alterations were correlated with poor survival in patients with lung adenocarcinoma (overall survival and disease-free survival) and as well as those diagnosed with bladder urothelial carcinoma (disease-free survival only)." (PMID 28978030, 2017).
colon cancer (2 papers, 2012 to 2025). "We found that PinX1 was elevated in most colon cancer cells compared with NCM460 cells." (PMID 40639785, 2025).
injury (2 papers, 2021 to 2022). Damage inflicted on the body as the direct or indirect result of an external force, with or without disruption of structural continuity. "However, PINX1-uregulation exhibited the highest expression of NF-κB p65 in lung tissues of LPS-induced lung injury rats." (PMID 33819185, 2021).
lentivirus infection (2 papers, 2015). Virus diseases caused by the Lentivirus genus. "After 3 weeks selection following with lentivirus infection, the PinX1 protein levels of these cell lines were confirmed by western blot." (PMID 25888829, 2015).
lung adenocarcinoma (2 papers, 2017). A carcinoma that arises from the lung and is characterized by the presence of malignant glandular epithelial cells. "There were more PinX1 homozygous deletions and PinX1 heterozygous deficiencies and less PinX1 amplifications in two specific NSCLC datasets (namely Lung Squamous Carcinoma – TCGA, Provisional and Lung Adenocarcinoma –TCGA, Provisional)." (PMID 28372542, 2017). "In addition, the frequency of PinX1 gene deletion in adenocarcinoma was more than squamous carcinoma in some solid tumors, such as 6.1% (TCGA, Nature), 5.5% (Broad, Cell), and 5.7% (TCGA, Provisional) in lung adenocarcinoma versus 1.7% (TCGA, Provisional) in lung squamous cell carcinoma." (PMID 28978030, 2017). "The deletion of PinX1 gene accounted for the most alterations and was visualized in six NSCLC database (Lung Adenocarcinoma – Broad, Cell 2012; TCGA, Provisional; TCGA, Nature 2014; TSP, Nature 2008; Lung Squamous Carcinoma – TCGA, Provisional; TCGA, Nature 2012)." (PMID 28372542, 2017).
melanoma (2 papers, 2017). A malignant, usually aggressive tumor composed of atypical, neoplastic melanocytes. "We reported increasing nucleolin expression with melanoma progression, which does not readily explain the trend for TERT; however we know of no data on PINX1 expression in melanoma." (PMID 29262649, 2017).
Obesity (2 papers, 2021 to 2022). Accumulation of substantial excess body fat. "It is worth noting that UTP14A, DKC1, and PinX1 are all closely associated with angiogenesis in various diseases, so we speculate that all three may affect cardiac angiogenesis in obesity, but their angiogenic roles in cardiac tissue remain unclear." (PMID 35734237, 2022). "In this study, UTP14A and PinX1 were identified as key genes in the heart of obese mice, which may be involved in the pathophysiology of obesity-related cardiac effects by regulating the balance of cardiac microvasculature, but there is no relevant research to verify this." (PMID 35734237, 2022). "UTP14A, DKC1, DDX10, PinX1, and ESF1 have been identified as hub genes in obesity-induced pathological changes in the heart and may be involved in obesity-induced cardiac injury by affecting cardiac microcirculatory function." (PMID 35734237, 2022). "UTP14A, DKC1, DDX10, PinX1, and ESF1 may be involved in obesity-induced cardiac injury by affecting angiogenesis in the heart." (PMID 35734237, 2022).
prostate adenocarcinoma (2 papers, 2014 to 2017). "The subcellular localization and expression of the PinX1 protein were observed and scored by IHC on the TMA, which including 40 prostate adenocarcinoma and 8 normal prostate tissues." (PMID 24936151, 2014).
Alzheimer disease (1 paper, 2020). A progressive, neurodegenerative disease characterized by loss of function and death of nerve cells in several areas of the brain leading to loss of cognitive function such as memory and language. "Pinx1 is a telomerase inhibitor with little known brain function, although variants have been associated with late-onset Alzheimer disease." (PMID 32174962, 2020).
bladder tumor (1 paper, 2013). "The IHC results demonstrated that negative expression of PinX1 protein in 44.4% of primary bladder tumor, but in only 20.6% of normal bladder epithelial tissues." (PMID 24268029, 2013).
carcinosarcoma (1 paper, 2017). A malignant tumor composed of a mixture of carcinomatous and sarcomatous elements. "Our results showed that PinX1 deletion accounted for the most alterations, with the frequency of its deletion regularly occurring in pathological types of carcinosarcoma and adenocarcinoma." (PMID 28978030, 2017). "Furthermore, the frequency of PinX1 deletion often occurred in the two specific pathological types of carcinosarcoma and adenocarcinoma." (PMID 28978030, 2017). "In addition, we also observed that the genotype of PinX1 gene deletion often occurred in both carcinosarcoma and adenocarcinoma." (PMID 28978030, 2017).
cervical cancer (1 paper, 2015). A primary or metastatic malignant neoplasm involving the cervix.
clear cell renal cell carcinoma (1 paper, 2015). "This study explored the clinical significance and biological function of PinX1 in human clear cell renal cell carcinoma (ccRCC)." (PMID 26033551, 2015). "Immunohistochemistry staining was utilized in TMA slides to evaluate the PinX1 expression in normal renal tissues, clear cell renal cell carcinoma tissues and paired adjacent non-tumor tissues." (PMID 26033551, 2015). "Moreover, univariate and multivariate Cox proportional hazards regression analysis investigated that low PinX1 expression was a strong independent negative prognostic indicator for clear cell renal cell carcinoma." (PMID 26033551, 2015).
colon adenocarcinoma (1 paper, 2025). "To investigate the role of PinX1 in cancers, we examined the expression levels of PinX1 in The Cancer Genome Atlas (TCGA) and GTEx database and found PinX1 was elevated both in colon adenocarcinoma (COAD) and rectum adenocarcinoma (READ) compared with the normal tissues." (PMID 40639785, 2025).
glioblastoma (1 paper, 2022). The most malignant astrocytic tumor (WHO grade IV). "In glioblastoma cell lines with induced overexpression of PINX1, there was a reduction in cell migration and proliferation due to cell cycle arrest at the G1 phase." (PMID 36142793, 2022).
osteosarcoma (1 paper, 2019). A usually aggressive malignant bone-forming mesenchymal neoplasm, predominantly affecting adolescents and young adults. "PinX1 involvement in a telomerase-independent mechanism that led to telomere dysfunction had been suggested in osteosarcoma cells." (PMID 31210926, 2019).
renal carcinoma (1 paper, 2024). A carcinoma arising from the epithelium of the renal parenchyma or the renal pelvis. "A recent study reported that PinX1 inhibited renal cancer angiogenesis via the VEGF signaling pathway." (PMID 39469202, 2024).
schizophrenia (1 paper, 2019). A major psychotic disorder characterized by abnormalities in the perception or expression of reality. "Several other genes in this region show suggestive evidence of differential expression/splicing in ASD, including MSRA, which has been previously associated with schizophrenia, MFHAS1, and PINX1." (PMID 31230729, 2019).
scleroderma (1 paper, 2021). Scleroderma is a rare autoimmune connective tissue disorder characterized by abnormal hardening of the skin and, sometimes, other organs. "PINX1 has been reported to be associated with systemic sclerosis (SSc (scleroderma)) in both African-American and White populations." (PMID 34337078, 2021).
cancer (32 papers, 2011 to 2025). A tumor composed of atypical neoplastic, often pleomorphic cells that invade other tissues. "Recently, our group discovered that that not only does PinX1 contribute to telomere maintenance, but it also affects cancer cell sensitivity to DNA damage caused by chemo-radiotherapy or chemotherapeutics." (PMID 28978030, 2017). "Furthermore, we demonstrated that PINX1 deficiency leads to susceptibility of cancer cells to PARP inhibitors both in vitro and in vivo, suggesting that its inhibition combined with PARP inhibitors can serve as a potential therapeutic strategy." (PMID 39174499, 2024). "Loss of PinX1 leads to increased telomere length contributing to the development of cancer." (PMID 34337078, 2021). "Owing to severe heterogeneity, subgroup analyses stratified by tumor type, sample size, test method, cutoff value, type of analysis, and NOS score were conducted to investigate the association between PINX1 expression and OS in patients with various types of malignant tumors." (PMID 30079348, 2018). "The pooled results for OS and DFS/RFS showed that low PINX1 expression was associated with poor prognosis, suggesting that PINX1 may function as a tumor suppressor gene in malignant tumors." (PMID 30079348, 2018). "Furthermore, our analysis of several human cancers from the cBioportal database revealed more frequent PinX1 homozygous depletion and PinX1 heterozygous deficiency, but both more infrequent PinX1 gain and rare instances of PinX1 amplification." (PMID 28978030, 2017). "It has been confirmed that PINX1 deficiency could lead to telomerase activation, telomere elongation and chromosome instability, however overexpression of PINX1 caused a decrease in both telomerase activity and cancer cell tumorigenicity." (PMID 29371971, 2017). "Pin2/TRF1 binding protein X1 (PinX1) has been identified as an endogenous telomerase inhibitor and a major haploinsufficient tumor suppressor gene localized at human chromosome 8p23, a region with frequent loss of heterozygosity in a number of human cancers." (PMID 24936151, 2014). "Therefore, PinX1 may be a new potential diagnostic biomarker and therapeutic target for human cancers, and may play different roles in different human cancers." (PMID 27556185, 2016). "Moreover, reducing PinX1 levels by heterozygous knockout or knockdown leads to chromosome instability and tumorigenesis in vitro and in vivo, with most tumors in PinX1+/- mice being carcinomas and sharing tissues of origin with human cancer types linked to 8p23." (PMID 22021332, 2011). "As a natural suppressor of telomerase, PinX1 represents a potential strategy for curtailing cancer progression by targeting telomerase." (PMID 39634130, 2025). "Overexpression of LPTS/PinX1 protein can inhibit the growth of multiple telomerase-positive cancer cell lines." (PMID 40896430, 2025). "Together, these results indicated that LPTS/PinX1 level is reduced in most human cancer tissues and cells and that LPTS/PinX1 is a major tumor suppressor." (PMID 40896430, 2025). "Collectively, PinX1 shortens telomeres and suppresses cancer stemness in CESC through the inhibition of telomerase activity, and TID with lysine residues clustered in PinX1292-301 are crucial for this suppressive effect." (PMID 39634130, 2025). "Complicated functions of PinX1 endow it with a versatile role in cancers, namely inhibiting malignancy in gastric, breast and renal cancer cells, or promoting proliferation in glioblastoma and prostate cancer cells." (PMID 40639785, 2025). "Then we investigated the impact of PinX1 on stemness-associated phenotypes and found that telomerase activity was closely correlated with cancer stemness in CESC and even in pan-cancer." (PMID 39634130, 2025). "Here, we unveil PIN2/TRF1-interacting telomerase inhibitor 1 (PINX1) as an uncharacterized PARP1-interacting protein that synergizes with PARP inhibitors upon its depletion across various cancer cell lines." (PMID 39174499, 2024).